OLIG2 (oligodendrocyte transcription factor 2)
Diseases named in the same sentence as OLIG2 in open-access papers (continued):
Sharing a sentence is not in itself a finding about the gene and the disease.
glioma (continued). "The enrichment pathways of C1 OLIG2+ Glioma cells for axis development, synapse organization, axionogenesis, glial cell differentiation, and regeneration of nervous system development suggest that this subpopulation may be involved in nervous system development and related tissue differentiation." (PMID 39403379, 2024). "It appears that Olig2 may be a therapeutic target in gliomas." (PMID 37274223, 2023). "Furthermore, we verified ACT001, a guaianolide sesquiterpene lactone in phase II clinical trial with excellent glioma remission, inhibited cancer stemness by directly binding to Olig2 protein, inducing Olig2 ubiquitination degradation and inhibiting CD133 gene transcription." (PMID 36990974, 2023). "Thus, targeting Olig2 or protein kinase inhibitors (PKIs) may have therapeutic effects against gliomas." (PMID 37274223, 2023). "Therefore, pharmacological inhibition of Olig2 may be therapeutically beneficial in treating gliomas." (PMID 37274223, 2023). "In addition, targeted therapies inhibiting OLIG2 in glioma are currently being tested in both laboratory and clinical settings including the use of a small inhibitory molecule that prevents the homodimerization of OLIG2 that subsequently impeding its nuclear localization." (PMID 34012965, 2021). "In the light of the finding that human and mouse low-grade gliomas are composed of Olig2+ cells and that Olig2+ oligodendrocyte precursor cells (OPCs) give rise to murine high-grade gliomas, we sought to determine whether Olig2+ OPCs could be tumor-initiating cells for Nf1 optic glioma." (PMID 28525381, 2017). "The prevalence of Olig2+ cells in human gliomas, coupled with recent findings that Olig2+ oligodendrocyte precursor cells (OPCs) are the cells of origin for murine malignant glioma, raises the possibility that OPCs might be another tumor-initiating cell population for Nf1 murine optic glioma." (PMID 28525381, 2017). "We thus investigated whether OLIG2 could serve as a therapeutic target in invading glioma cells." (PMID 25365423, 2014). "In addition to the proneural glioma subtype, Olig2 may also play a role in the mesenchymal glioma subtype." (PMID 23451236, 2013). "Indeed, Olig2-expressing (Olig2+) oligodendrycyte precursor cells (OPCs) may be candidate cells of origin in a mouse model of glioma, as well as human diffuse intrinsic pontine glioma (DIPG), an aggressive and almost universally fatal childhood brain tumor." (PMID 23451236, 2013). "Interestingly, both Sox2 and Olig2 have been ascribed important roles in maintaining self-renewing stem cells in the CNS and this activity appears, at least in part, to be conserved in gliomas." (PMID 21483788, 2011). "Based on the function of Id4, OLIG1, and OLIG2 during normal development, our data suggest that Id4 and potentially other genes such as Fabp7 and Ptprz1 might account for the formation of distinct glioma subtypes during oncogenic progression." (PMID 16018821, 2005). "For most of these models, histopathological analyses revealed highly proliferative tumors showing features of human high-grade glioma including necrosis, pleomorphic nuclei, and positive staining for glial cell markers (GFAP and/or OLIG2)." (PMID 41381884, 2026). "To further investigate the relationship between LDH isoenzymes and PMT in glioma, we analyzed protein expression levels of VIM (mesenchymal marker) and OLIG2 (proneural marker) through western blotting." (PMID 39895794, 2025). "The ATRX, OLIG2, MGMT, and IDH2 networks highlight key molecular interactions that contribute to glioma development, progression, and therapeutic resistance." (PMID 40282990, 2025).
glioma (continued). "Clusters with high entropy were further validated to exhibit the elevated expression of canonical glioma stem-like cell markers (SOX2, OLIG2, PROM1), supporting their classification as high-stemness populations beyond theoretical entropy alone." (PMID 40806540, 2025). "HOXDeRNA promoted astrocyte transformation by releasing PRC2 repression at glioma transcription factor promoters (SOX2, OLIG2) and activating super enhancers, leading to oncogene upregulation." (PMID 41154382, 2025). "In TCGA glioma samples, USP14 showed positive correlation with CD44 and ALDH1A3, and inverse correlation with PN markers, SOX2 and OLIG2." (PMID 39990235, 2025). "These two tumor types were specifically chosen because they contained “mixed glioma” cell types, co-expressed both ASCL1 and OLIG2, but exhibited completely different migratory behavior." (PMID 39609428, 2024). "In vivo, glioma stem cells (GSCs) with tumor self-renewal ability and aggressive growth metastasis are typically found in the perivascular niche, expressing SOX2, OLIG2, and NESTIN." (PMID 38390494, 2024). "METTL3 silencing reduced the expression of the glioma reprogramming factors POU3F2, SOX2, SALL2 and OLIG2, and suppressed GSC proliferation in neurosphere assays derived from human glioma cell lines." (PMID 37444417, 2023). "In contrast, key regulators of OPC specification and maintenance, including MYT1, OLIG2, PDGFRA, PTPRZ1, SMOC1, and SOX8 were hypomethylated in PM gliomas." (PMID 37055795, 2023). "OLIG2, when unphosphorylated, drives TGF‐β2 expression and promotes glioma cell migration and aggressiveness." (PMID 37786890, 2022). "QPP tumors demonstrated a trend of increased staining densities for GBM-indicative protein markers such as Olig2, Gfap, and Iba1, while the PP and PPP tumors displayed histological characteristics similar to the lower-grade gliomas." (PMID 36051438, 2022). "BMP‐4 reduced the expression of glioma stem cell marker mRNAs, including PROM1, OLIG2, and SOX2, in TGS‐01 as well as in TGS‐04 cells." (PMID 34214250, 2022). "The mechanism is that unphosphorylated OLIG2 induced TGF‐β2 expression and promoted the aggressive mesenchymal properties of glioma cells." (PMID 37786890, 2022). "Proneural glioma are defined by the expression of the neurogenesis markers PDGFRA, NKX2-2, and OLIG2, and they are IDH1 mutants." (PMID 35328529, 2022). "The transcription factors OLIG2 and SOX10 are expressed in all cells of the oligodendrocyte lineage, and these TFs exhibit broad expression across the glioma subtypes." (PMID 34976314, 2022). "Knockdown of HDAC1 resulted in a significant decrease in the expression of glioma master transcription factors SOX2 and OLIG2, stem cell marker NESTIN, and the receptor tyrosine kinase epidermal growth factor receptor (EGFR)." (PMID 34494550, 2021). "The level of expression glioma-characteristic genes (e.g. CD34, GFAP, OLIG2, MAP2, MKI67, RBFOX3, SOX2, SYN; Suppl." (PMID 34545083, 2021). "Immunofluorescent staining confirmed that WISP1 was preferentially expressed in glioma cells expressing the GSC markers SOX2 and OLIG2, and was enriched in the proximity of GSCs." (PMID 32541784, 2020).
glioma (continued). "Thus, a trend towards negative prognostic impact of higher Olig2 expression could be explained by the association with a higher frequency of glioma stem cells and consequently, a worse prognosis." (PMID 32160197, 2020). "Recently, it has been reported that strong expression of glial markers, including GFAP, S100β, and OLIG2, and elevated p-ERK levels are observed in the glioneuronal tumors or glioma of NS patients." (PMID 32493428, 2020). "Overall, our findings illustrate that ASCL1, OLIG2, and SOX2 are coexpressed in tumor cells of both early and terminal tumors of the glioma mouse model in vivo, and tumor cells maintain a molecular identity reminiscent of that of OPCs." (PMID 32573857, 2020). "The tumor cells of xenografts maintained the key immune-phenotype of patient gliomas, as determined by staining using GFAP, vimentin and OLIG2." (PMID 31908598, 2020). "Immunofluorescent staining confirmed that CBP was highly expressed in nuclei of glioma cells expressing the GSC markers SOX2 and OLIG2 in primary human GBMs." (PMID 33124191, 2020). "OLIG2, which exhibited significantly different expression between GC-GBM and MS-GBM, is commonly expressed in glioma and has also been identified as a transcription factor that reprograms differentiated GBM cells into stem-like cells." (PMID 31655917, 2020). "These spinal tumors expressed classical glioma markers, such as GFAP, Sox2, Olig2, and PDGFRa, and had a lower proliferative index than the corresponding brain tumors." (PMID 32727536, 2020). "The change in m6A modification and the transcript level of four glioma reprogramming factors (SOX2, SALL2, OLIG2 and POU3F2) and selected transcripts were validated by m6A RIP-PCR and RT-qPCR." (PMID 30781903, 2019). "This transcription factor has a recognized oncogenic role in glioma growth 64, however in MVNT OLIG2 expression is noted in the context of overall reduced myelination and labelling of VC for myelin basic protein." (PMID 28833756, 2018). "In slowly growing gliomas, cells expressed NG2/CSPG4, as well as Olig2, Sox10, and Nkx2.2, all markers of committed progenitor cells to the oligodendroglial lineage, but not O4, a marker of late and adult OPCs." (PMID 30213051, 2018). "As a whole, all these observations are in line with the origin of most gliomas from the subcortical white matter rich in OPCs expressing NG2/CSPG4, PDGFRα, and Olig2." (PMID 30213051, 2018). "Treatment with SI113, alone or in combination with EPO-A or VCR, yielded a modification of mRNA expression for OCT3/4, NANOG, NESTIN and OLIG2, all GBM or glioma stemness markers." (PMID 29340013, 2017). "Histologically, the tumours were similar to those generated in the orthotopic implantation studies, and were positive for the glioma markers GFAP and Olig2." (PMID 28695888, 2017). "Olig2 and GFAP co-labeling demonstrated numerous glial tumor cells (OLIG2+) invading through and within a peri-tumoral band of reactive astrocytes (GFAP+) in the tumor margin." (PMID 28358926, 2017). "Finally, in addition to its expression in adult oligodendroglia, Olig2 is a key driver of tumor growth and proliferation, and is part of a core set of neurodevelopmental transcription factors capable of reprogramming differentiated glioma cells into stem-like tumor-propagating cells." (PMID 29049317, 2017). "nf1a+/−/nf1b−/− mutants in the p53zdf1/zdf1 background developed brain tumors in 33 weeks, with characteristic markers (sox10/Olig2/Gfap) of diffuse high-grade gliomas and hyperactivation of ERK and mTOR pathways, similar to mouse models and human gliomas." (PMID 28930163, 2017). "The expression of CD133, Olig2 and CD44 was investigated using patient derived glioma stem-like cells (PDGCs) in vitro and in vivo." (PMID 28241049, 2017). "Both microarray data of ERBB4 and Olig2, two known PN subtype signature genes, show significantly different expression levels between grade III and IV gliomas in GDS1815 dataset (p = 0.01 and 0.005, respectively)." (PMID 26614510, 2016).
glioma (continued). "Exposure to glioma-related mitogens EGF and PDGF leads to proliferation of OLIG2+ rapidly dividing cells (type C)." (PMID 27447975, 2016). "NG2+ cells that often co-express PDGFRα and Olig-2 are present in adult gliomas, where NG2 contributes to the neoplastic transformation of glioma precursor cells." (PMID 25987129, 2015). "Nearly 30% of human gliomas show expression patterns that are correlated with PDGFR signaling, a pattern with prominent expression of OLIG2 and other genes involved in CNS development referred to as “proneural”." (PMID 21754979, 2011). "Furthermore, SUV39H1 expression was positively correlated with SOX2 and OLIG2 expression in GBM samples from the TCGA and Chinese Glioma Genome Atlas (CGGA) databases." (PMID 40059829, 2025). "Olig2, GFAP, and vimentin are frequently used for glioma subtyping." (PMID 40362055, 2025). "We classified the 40,650 astrocytomas obtained by Seurat and named the seven subclusters according to the marker genes as C0 IGFBP7+ Glioma cells, C1 OLIG2+ Glioma cells, C2 LINC02283+ Glioma cells, C3 LINC00632+ Glioma cells, C4 MX1+ Glioma cells, C5 FOSB+ Glioma cells, and C6 DLL3+ Glioma cells." (PMID 39403379, 2024). "The value of the glial marker S100 in the characterization of xenografts appeared limited in our study as the glial tumors with a high IHC score for Olig2 exhibited a weak or absent S100 immunostaining." (PMID 38098992, 2023). "Reciprocally, overexpressing OLIG2 induced INHEG in patient-derived GSCs and glioma cells." (PMID 37980347, 2023). "A brain lesion biopsy revealed a high-grade infra-tentorium IDH-1 and IDH-2 wild-type glial tumor, GFAP and Olig2 positive and histone H3‐K27M mutation-negative (glioblastoma, grade 4 WHO 2021)." (PMID 37692853, 2023). "OPGs are low-grade gliomas with features that include a low proliferation index as well as glial fibrillary acidic protein (GFAP) and oligodendrocyte transcription factor 2 (OLIG2) immunoreactivity, and they are often slow-growing." (PMID 37891793, 2023). "A stereotactic brain biopsy and subsequent neuropathological evaluations were performed, resulting in a glioma tumor isocitrate dehydrogenase 1 (IDH-1) and 2 (IDH-2) wild type, glial fibrillary acidic protein (GFAP) and oligodendrocyte transcription factor 2 (Olig2) positive." (PMID 37692853, 2023). "Using Western blotting analysis and immunostaining, we did not detect the OLIG2 protein expression in all tested glioma cell lines growing in serum-containing media." (PMID 36900355, 2023). "The authors discovered that Olig2+ (Wnt7 wildtype) glioma cells used VCO, while Wnt7 null glioma cells did not migrate along blood vessels via VCO." (PMID 36119528, 2022). "These cells usually express some specific stem markers, like CD-133, OLIG2, and SOX2, in gliomas." (PMID 36338770, 2022). "The results showed that ME2 overexpression in SW1783 and U251MG cells upregulated the expression of N-cadherin, vimentin, YKL40, and MET expression, whereas it downregulated the expression of E-cadherin and OLIG2, suggesting that ME2 promotes PMT of glioma cells." (PMID 34381734, 2021). "Furthermore, we observe that ablation of HDAC1 function in GSCs suppressed expression of key glioma stemness markers like SRY-box transcription factor 2 (SOX2), Nestin, and oligodendrocyte transcription factor 2 (OLIG2)." (PMID 34494550, 2021). "To interrogate the functional significance of SATB2 expression in GBM malignant growth, we initially examined SATB2 expression pattern in several human GBM specimens and found that SATB2 is preferentially expressed in nuclei of glioma cells expressing the GSC markers SOX2 and OLIG2." (PMID 33124191, 2020). "We included into the custom set three probes for genes expressed in glioma tumors (GFAP, OLIG2 and PMP2), in addition to the CNS HGNET-BCOR marker probes, and performed hybridization in the series of 27 tumors originally diagnosed as HGG and one HGG relapsed sample." (PMID 32650833, 2020).
glioma (continued). "In U87 glioma cell, suppression of LICN01503 could significantly inhibit the expression of CD44, but increase OLIG2 expression, suggestive of mesenchymal-to-proneural transition." (PMID 33028341, 2020). "This is consistent with the origin of most gliomas from the subcortical white matter that is rich in OPCs expressing NG2/CSPG4, platelet-derived growth factor alpha (PDGFRα), and oligodendrocyte lineage transcription factor 2 (Olig2)." (PMID 32599896, 2020). "This absence of Olig2 staining suggested that these glioma-like lesions were not DIPGs as Olig2 is a robust marker of DIPG tumor cells." (PMID 30833574, 2019). "More recently, the kinases responsible for OLIG2 phosphorylation have been identified and targeted by small molecule inhibitors that reduce gliomagenesis and increase survival in a BRAFV600E mouse model of paediatric glioma." (PMID 29759978, 2018). "Histological examination and Olig2 immunohistochemical staining confirmed the presence or absence of glioma lesions in all of the mice (data not shown)." (PMID 30416682, 2018). "Importantly, OLIG2 phosphorylation is involved in a positive regulatory loop with receptor tyrosine kinases such as EGFR, which is essential for glioma stem cell maintenance in vitro." (PMID 29759978, 2018). "Potentially acting as a lineage-specific oncogene, OLIG2 is expressed in all cases of diffuse paediatric and adult human gliomas regardless of grade." (PMID 29759978, 2018). "Diffuse gliomas expressed NG2/CSPG4, PDGFRα, and Olig2, that are characteristic of OPCs." (PMID 30213051, 2018). "Our immunofluorescence staining identified that OLIG2 positive cells are co-localized with CMV glycoprotein B. These data suggest that a precursor of GSC, OLIG2 positive NSC, can be a source for CMV persistence in the glioma tissue." (PMID 27517625, 2017). "Expression of Olig2 and VEGF in all high-grade gliomas and glioma stem cells may render them highly vascular." (PMID 23516171, 2013). "It appears that there may be common genetic gatekeepers, such as Olig2 and SHH, for neurodevelopment and glioma formation." (PMID 19777070, 2009). "Olig2 positivity, while commonly seen in gliomas, is not exclusive to any specific glioma subtype." (PMID 40034891, 2025). "Finally, glioma initiation and formation were completely compromised in the majority of Ascl1;Olig2-dCKO mice, highlighting the redundant function of ASCL1 and OLIG2 as prominent transcription factors hijacked by tumor-initiating events." (PMID 39609428, 2024). "Olig2, a protein-coding gene commonly expressed in gliomas independent of WHO tumor grade." (PMID 38418976, 2024). "Additionally, NeuN+ and Olig2+ cells were mutually exclusive, further suggesting that DNTs are clear glial tumors rather than glioneuronal tumors." (PMID 37274223, 2023). "In glioma, inhibiting STAT3 activation by pharmacological or genetic means has been shown to reduce Olig2 levels, observations that may tie together lucanthone’s mechanism with the observed reduction in Olig2." (PMID 35494072, 2022). "SOX10, a transcription factor that interacts with Olig2, is important in non-neoplastic oligodendroglial development, and the dys-regulation of mRNA transcripts and protein expression are identified in a wider variety of CNS glial neoplasms." (PMID 35729639, 2022). "Mechanistically, we could not detect an influence of TAL1 and SLUG on the two key glioma transcription factors we explored (OLIG2 and SOX2) so their specific downstream targets remain to be fully identified." (PMID 34771555, 2021). "To determine whether ME2 promotes PMT of glioma cells, we performed a western blot assay to detect the expression of MES markers MET, YKL40, N-cadherin, and vimentin; epithelial marker E-cadherin; and PN marker OLIG2." (PMID 34381734, 2021).